CD44 (CD44 molecule (IN blood group))
Diseases named in the same sentence as CD44 in open-access papers (continued):
Sharing a sentence is not in itself a finding about the gene and the disease.
breast carcinoma (continued). "Studies have shown that CD44/CD24 and ALDH1 expressed differently in different subtypes of breast cancers." (PMID 29062075, 2017). "In conclusion, the results illustrated that in CD44+Fbs, binding of IGF2BP3 and CD44 promotes IGF2 expression and then accelerates breast cancer cell proliferation, survival and induced chemotherapy resistance likely by activating Hedgehog signal pathways." (PMID 28523716, 2017). "BAG3 significantly promoted BCSC-like properties as evidenced by increase in the fraction of CD44+/CD24− subpopulation, as well as a significant increase in the number and size of mammospheres derived from breast cancer cells." (PMID 28703799, 2017). "Several studies have shown that a sub-fraction of breast cancer cells termed BTICs undergo EMT reprogramming and typically exhibit a basal-like CD44+/CD24- phenotype harboring cancer stem-like features." (PMID 29207686, 2017). "Among 9 breast cancer cell lines examined, 3 cell lines (MDA-MB-231, BT-549, and HCC1937) contained a relatively higher percentage (>30%) of CD44+/CD24− cells, indicating that the high percentage of CD44+/CD24− cells directly associates with a basal phenotype." (PMID 29197410, 2017). "We investigated the expression of CD44, CD24 and ALDH1 in different subtypes of breast cancer cells, and explored their relationship with cancer progression." (PMID 29062075, 2017). "The expression of NMI was downregulated in breast cancer mammospheres compared with primary breast cancer and NMI was also downregulated in the CD44+CD24− cells compared with the CD44−CD24+ cell populations." (PMID 28492540, 2017). "It illustrated that the other breast cancer stem cells such as MDA-MB-436 and Hs578T, which contained CD44+/CD24− population, also naturally established the inhibitory effect." (PMID 28718836, 2017). "Specifically, it has been shown that the WNT5A-mediated suppression of CD44 reduces the downstream AKT signaling, which further explains how WNT5A signaling impairs breast cancer cell migration and invasion." (PMID 28886116, 2017). "In order to evaluate the expression of DACH1 and CD44 in normal breast and breast malignant tissues, we carried out IHC analysis on two TMAs (BR1502–97 and BR1502-98) with normal breast and human breast cancer tissues." (PMID 28659634, 2017). "Previous studies indicate that breast cancer cells with high aldehyde dehydrogenase (ALDH) activity and CD44 expression (ALDHhiCD44+) contribute to metastasis and therapy resistance, and that ALDH1 correlates with poor outcome in breast cancer patients." (PMID 28937653, 2017). "To study the relationship of CSCs and metastasis in breast cancer, we analyzed CSC contents of the isogenic MCF10 cancer cell lines by cell flow cytometry (FACS) with the prevailing markers CD24 and CD44." (PMID 28300837, 2017). "To evaluate the CSC properties in MCF7 and doxo-resistant MCF7/ADR cells, we first evaluated the population of CD44+/CD24- and ALDH+ cells, which have been reported as the best markers for identification of breast cancer stem cells." (PMID 29050299, 2017). "To check the response of LDR in breast cancer, we initially examined a CD44+/CD24− population, i.e., those survived within breast cancer and maintained stemness, in LDR-exposed MDA-MB231 breast cancer cell lines." (PMID 28240233, 2017). "The primary outcome will be the expression pattern of circulating CSC markers in breast carcinomas including EPCAM, CD44, CD24, ALDH1, CD133, and PIWIL2." (PMID 29258583, 2017). "Immunofluorescence results revealed that the isolated CTCs from the advanced breast cancer patient exhibited high expression of CD44 and ALDH1, indicating the conservation of these two stem markers in CTCs from breast cancer patients." (PMID 29062075, 2017).
breast carcinoma (continued). "Cancer cells from TNBC often display a profile of cell surface markers that are similar to that of breast cancer stem cell (BCSC), characterized by the phenotype CD44+/CD24− in which CD44 is expressed at high levels but levels of CD24 are low or undetectable." (PMID 28760736, 2017). "This suggests that both CD44 and RGD-dependent integrins can mediate the tumorsphere-forming capacity of breast cancer cells through interactions with OPN." (PMID 28498874, 2017). "Our data show that SID peptide downregulates Wnt/β-catenin reporter activity and direct Wnt target genes (LEF1, TCF7L2, CD44, PLAU, MT1-MMP, MMP9, HMGA2) involved in breast cancer invasion and metastasis." (PMID 29179446, 2017). "hATT-CMs increase versican, CD44, ADAMTS1 and Adipo R1 expression in breast cancer epithelial cells." (PMID 28173833, 2017). "TNBC phenotypes, which are usually enriched for CD44+/CD24− CSCs, also displayed higher ACTN4 expression than other breast cancer subtypes." (PMID 29197410, 2017). "In comparison to patient tumors, breast cancer cell lines differentially expressed ALDH, CD44 and/or CD24, making interpretation of experimental results difficult." (PMID 29348905, 2017). "In breast cancer cells, the lipid-modified glycoprotein, WNT5A, inhibits metastasis and alters the splicing of CD44." (PMID 29190904, 2017). "To this end, we tended to explore the dynamic changes of the CD44/CD24 ratio and the expression of ALDH1 during the development and metastasis of breast cancer." (PMID 29062075, 2017). "In breast cancer, for example, WNT5A is known to inhibit cell migration and invasion partly by reducing the levels of CD44." (PMID 28886116, 2017). "We identified an association between metastasis-related properties of TRAP-overexpressing MDA-MB-231 breast cancer cells and a TRAP-dependent regulation of Transforming growth factor (TGFβ) pathway proteins and Cluster of differentiation 44 (CD44)." (PMID 28915803, 2017). "Lastly, as CD44+ and CD24− cells are well-known stem cell markers in breast cancer, we quantified the frequency of the CD44+/CD24− cell population within TNBC cell lines." (PMID 28427212, 2017). "We show that CD74 and CD44 molecules are detectable by flow cytometry in CAMA-1, MDA-MB-231 and MDA-MB-435 breast cancer cells." (PMID 29190904, 2017). "Because expression of the CD44 stemness marker promotes chemoresistance in breast cancer cells, we investigated the extent to which SMAD5 activity was required to induce CD44 expression in MDA-MB 231 cells." (PMID 29207686, 2017). "In support of this conclusion, our immunohistochemical assays performed in clinical breast cancer samples also shown an inverse correlation between the expression levels of BMP-2 and Rb and a positive correlation between BMP-2 and CD44." (PMID 28725489, 2017). "Our further research for the molecular mechanism showed that IGF2BP3 bound to CD44 mRNA and enhanced CD44 expression, which increased IGF2 levels of fibroblasts and then stimulated breast cancer cell proliferation and drug resistance." (PMID 28523716, 2017). "Using aldehyde dehydrogenase (ALDH) activity as an intracellular marker and CD44+/CD24−/low as cell surface markers, we were able to identify and quantify CSC population within breast cancer cells." (PMID 29156633, 2017). "Most recently, EpCAM, CD44 and MET have also been identified in circulating tumor cells (CTCs) of breast cancer patients exhibiting metastasis." (PMID 26243458, 2016). "We clearly showed that WNT5A suppresses CD44, which consequently reduces downstream AKT signaling in breast cancer cells." (PMID 27623766, 2016). "Based on a number of basic studies, the combination of CD44 and CD24, or aldehyde dehydrogenase 1 (ALDH1) alone, is a widely used CSC marker in breast cancer." (PMID 27768764, 2016).
breast carcinoma (continued). "Together, these results strongly suggest that blocking CDK4 activity leads to increased expression of the differentiation factor BMP4, resulting in decreased CD44+/CD24− BCSC numbers, and further leading to inhibition of breast cancer stemness." (PMID 27759034, 2016). "The combination of CD44 and CD24, or aldehyde dehydrogenase 1 (ALDH1) alone, is a widely used cancer stem cell marker in breast cancer." (PMID 27768764, 2016). "In summary, we demonstrate that CD74 promotes breast cancer cell metastasis, that CD74 and CD44 coordinately upregulate CFL1 phosphorylation through RHOA pathway, and that the repression of CD74 expression suppresses xenograft growth in vivo." (PMID 27626171, 2016). "Breast cancer cells that express less CD24 and more CD44 are more de-differentiated and more stem cell-like." (PMID 26832928, 2016). "CD44+/CD24−or low cells isolated from breast cancer cell lines and breast cancer patient specimens were radioresistant, and this resistant phenotype was associated with ATM signaling activation." (PMID 26682001, 2016). "Basal-B cells express high CD44 and CDK4, along with high levels of the mesenchymal marker vimentin, while basal-A or luminal-like breast cancer cells display higher CD24 level with a high expression level of the epithelial marker E-cadherin." (PMID 27759034, 2016). "When different digestive agents were compared with regards to their effect on the presence of CD44 and CD24 surface markers in a breast cancer cell line, differences were observed." (PMID 27766946, 2016). "For example, the CSC surface markers CD44+ and CD24− were defined in breast cancer, CD20+ and ABCB5+ in melanoma, and EpCAM+, CD44+, and CD166+ in colon cancer." (PMID 27172898, 2016). "To isolate BCSCs, we used specific antibodies against surface markers (CD44, CD24 or Epithelial Cell Adhesion Molecule (ESA) in a luminal (MCF7) and a triple negative (MDA-MB-231) breast cancer cell line." (PMID 27876836, 2016). "In a study with breast cancer cells (MDA-MB-231, MDA-MB-436, Hs578T, SUM1315, and HBL-100 cell lines) having CD44+/CD24− subpopulation showed higher levels of expression of proinvasive genes and had highly invasive properties." (PMID 27200096, 2016). "The different number of cells positive for vimentin, nuclear β-catenin, and CD44 expression, in high-grade ductal infiltrating carcinoma, as compared to low-grade carcinoma and benign lesions suggested that the process of de-differentiation of breast cancer cells could be related to the EMT." (PMID 27429011, 2016). "Futher research showed that breast cancer cells with EMMPRIN knocking-down exhibits a CD44−CD24+ phenotype and cells with human recombinant EMMPRIN exhibites a CD44+CD24− phenotype." (PMID 27325313, 2016). "The pairing of CD44 and CD24 was first employed to select for TICs in solid tumors, leading to observations that in breast cancer the CD44High/CD24Neg/Low sub-population has enriched TIC activity." (PMID 27001172, 2016). "A similar link was also observed between the CD44+/24–/low profile and BRCA1 expression status in basal–like breast cancer cells, as HCC1937 expressed higher CD44+/24–/low cells than the HCC1937/wt BRCA1 cell line." (PMID 27229859, 2016). "The aggressive TNBCs of basal origin showed a high expression of CD44+/24–/low cells with MDA-MB-231 and MDA-MB-436 that formed normal like breast cancers exhibiting higher levels of these putative BCSCs." (PMID 27229859, 2016). "CD44 also activates the transcriptional regulator Nanog and c-Jun N-terminal kinase (JNK) in breast cancer cells." (PMID 27009862, 2016). "The expression level of CDK4, CD44, and CD24 was analyzed in 51 breast cancer cell lines containing mesenchymal-like (basal-B) and epithelial-like (basal-A and luminal) phenotypes." (PMID 27759034, 2016).
breast carcinoma (continued). "Because CD44 overexpression alone is sufficient to induce breast cancer cell migration and invasion, we investigated the ability of WNT5A signaling to directly regulate CD44 expression in breast cancer cells." (PMID 27623766, 2016). "Breast cancer stem cells, identified as a CD24-/CD44+ enriched population growing as spheres, showed increased resistance to irradiation when compared to a non-enriched, monolayer culture." (PMID 27028405, 2016). "The present study demonstrated that WNT5A signaling can suppress CD44 protein expression and signaling, which supports the use of a WNT5A agonist in the treatment of breast cancer patients." (PMID 27623766, 2016). "This study demonstrated that WNT5A inhibits CD44 expression and its downstream AKT signaling, which further explains how WNT5A signaling impairs breast cancer cell migration and invasion." (PMID 27623766, 2016). "CD44 also has an effect on cell morphology, and the breast cancer cells with CD74 or/and CD44 knockdown exhibited a smoother cell edge with fewer protrusions." (PMID 27626171, 2016). "Exogenous CD44 3′UTR increased the expression of CD44, Col1α1, and FN1, resulting in enhanced cell motility, invasion, and cell adhesion in the breast cancer cell line MDA-MB-231." (PMID 26872371, 2016). "The identified shRNAs target genes involved in signaling pathways known to regulate breast cancer stem cells, including WNT (SFRP1), CD44 (FKBPL), and the PI3K/AKT (FOXO3A) signaling pathways." (PMID 26595803, 2016). "Stemness-enriched breast cancer cells have a CD44+/CD24− phenotype and higher NF-κB activity than CD44−/CD24+ breast cancer cells." (PMID 28116318, 2016). "A comparison of the variations in the percentages of SP, CD44+/24–/low and ALDH1+ cells among breast cancer cell lines of different origins with varied receptor status has not been reported." (PMID 27229859, 2016). "Using cell markers, such as CD44+/CD24-/low and ALDH positivity, is an additional method that differentiates between BCSCs and breast cancer cells." (PMID 27976692, 2016). "The effect of simvastatin on sphere forming capacity was therefore investigated in the canine mammary cancer cell line, CF41 Mg, which is enriched for CD44+/CD24−/low cells." (PMID 27993142, 2016). "Using the combination of anti-CD24, anti-CD44 and anti-epithelial-specific antigen (ESA) antibodies, the authors dissociated nine primary or metastatic human breast cancer samples." (PMID 27993142, 2016). "The study indicates that CD44, CD47 and c-met are the biomarkers of metastasis-initiating cells of breast cancer." (PMID 25658794, 2015). "Our results showed that DSF can inhibit the self-renewal capability of breast cancer cells, and reverse the expression of breast CSC markers, such as ALDH, CD44 and CD24." (PMID 26517513, 2015). "It was also reported that miR-34a inhibits proliferation, migration, and invasion of breast cancer cells by targeting several genes including E2F3, CD44, and SIRT1, Notch1 and DLL1." (PMID 25826085, 2015). "Therapy-resistant breast cancer cells have a common phenotype of CD44+/CD24−/low, in which CD44 is a transmembrane hyaluronan (HA) receptor." (PMID 26448751, 2015). "In 2013, Baccelli studied metastasis of circulating tumor cells in the blood of breast cancer patients and reported that metastasis-initiating cells had an EPCAM+CD44+CD47+c-met+ phenotype." (PMID 25658794, 2015). "hnRNPM-mediated CD44 exon skipping was induced through inhibition of ESPR1 function and was essential for breast cancer metastasis." (PMID 25904917, 2015). "In 2013, Baccelli studied the metastasis of circulating tumor cells in the blood of breast cancer patients and reported that metastasis-initiating cells had an EPCAM+CD44+CD47+c-met+ phenotype." (PMID 25658794, 2015).
breast carcinoma (continued). "To identify whether flubendazole inhibits breast cancer stem-like cells, we performed flow cytometry analysis to analyze the proportion of CS-like cell subpopulation in breast cancer cells based on the expression of CD44 and CD24 (CD44high/CD24lowconfiguration)." (PMID 25811972, 2015). "CD44+/CD24- subpopulation has been found to be enriched with tumor-initiating features, especially in breast cancer cells." (PMID 26185996, 2015). "RHAMM, CD44, and ERK1/2 are in a signaling complex and can be co-immunoprecipitated from MDAMB231 and Ras-MCF10A breast cancer cells; this complex promotes sustained high basal motility." (PMID 25954275, 2015). "The mammosphere cells were separated and characterized for surface expression of CD44 and CD24, which are commonly considered as markers of breast cancer stem cells." (PMID 26315028, 2015). "Similar to reports in breast cancer cells, we observed leptin-induced expression of EMT genes and stemness markers in CICs isolated from ovarian cancer (CD44+), supporting its role in the maintenance of a more aggressive phenotype." (PMID 26053184, 2015). "Given our prior demonstration that elevated CD44 expression may initiate adhesion of cells to distant endothelial monolayers, the objective of this study was to characterize the importance of CD44 in regulating post-intravasation events and distant metastasis of breast cancer in vivo." (PMID 25888636, 2015). "CD44+CD24−/lowESA+ cells have been reported to possess tumorigenic properties, and these biomarkers are thought to be highly expressed in breast cancer stem cells." (PMID 25905435, 2015). "The HA-CD44-mediated TGF-β1 and EGF signaling, and the co-localization of CD44/EGFR had an effect on the activation of EGF signaling induced by TGF-β1 in lung and breast cancer cells." (PMID 26005723, 2015). "When STAT3 is knocked down in MCF7–HER2 breast cancer cells, the expression of CSC markers CD44, Oct-4, and Sox-2 was downregulated, resulting in decreased tumor sphere formation." (PMID 25954275, 2015). "The expression of respective proteins (Trop2, CD49f, c-Met, CK8, CD44, ADAM8, CD146, TEM8, CD47) was verified by immunofluorescence on EpCAMpos (e.g. MCF7, SKBR3) and EpCAMlow/neg (MDA-MB-231) breast cancer cell lines." (PMID 26695635, 2015). "Numerous studies have reported that CD44+/CD24− epithelial tumor cells are the most common in TNBC, but the relationship between CD44+/CD24− cells and prognosis in breast cancer is debated." (PMID 25429827, 2015). "We also determined that the cell proliferation of breast cancer MDA-MB231 and MCF-7 cells was significantly reduced by CD44 ablation." (PMID 25909162, 2015). "In our experiment, induction of EMT in breast cancer cells by exposure of TGF-β resulted in the acquisition of stem-like expression pattern (ALDH+, CD24− /CD44+) and self-renewal capacity." (PMID 26517513, 2015). "Other studies have also observed this switch through the interconversion of CD44− in CD44+ prostate cancer cells and ABCG2− in ABCG2+ breast cancer cell as a result of microenvironmental changes." (PMID 26452033, 2015). "In this study, we demonstrated how the cleaved intracellular domain of CD44 (CD44ICD) activates stemness factors such as Nanog, Sox2 and Oct4, and contributes to the tumorigenesis of breast cancer." (PMID 25909162, 2015). "The anti-cancer effects of resveratrol were studied in CD24−/CD44+/epithelial specific antigen (ESA)+ populations of cancer stem cells selected from MCF-7 and MDA-MB-231 breast cancer cell lines." (PMID 26694341, 2015). "Our results demonstrated that DSF treatment suppressed the expression of breast CSCs markers (ALDH+, CD44+/CD24−), and abolished the sphere-forming ability in breast cancer cells at a concentration of 10–15 μM." (PMID 26517513, 2015).